VASN (vasorin)
Description:
May act as an inhibitor of TGF-beta signaling.
Synonyms: SLITL2
Tractability: Antibody: UniProt places it where antibodies can reach, with high confidence; UniProt predicts a signal peptide or a membrane-spanning region; its Gene Ontology location is reachable by antibodies, with medium confidence. PROTAC: ubiquitination databases record sites on it.
Gene: Protein-coding gene on chromosome 16 (4,371,848 to 4,383,538, forward strand). Ensembl gene ENSG00000168140.
Subcellular location: Membrane; Secreted
Subcellular location (Human Protein Atlas): Mitochondria; Nucleoli; Nucleoplasm; Predicted to be secreted
Gene Ontology:
Molecular function: cadherin binding; protein binding; transforming growth factor beta binding; signaling receptor activity
Biological process: negative regulation of epithelial to mesenchymal transition; negative regulation of transforming growth factor beta receptor signaling pathway
Cellular component: cell surface; extracellular exosome; extracellular region; lysosomal membrane; plasma membrane; membrane; mitochondrion
Genetic constraint (gnomAD): Loss-of-function variants: 13 observed, 9.26 expected, observed/expected ratio (o/e) 1.4, 90% interval 0.9 to 1.9. That is too few expected variants to judge how well the gene tolerates losing a copy. Missense variants: 927 observed, 852.15 expected, observed/expected ratio (o/e) 1.09, 90% interval 1.03 to 1.15. Synonymous variants: 499 observed, 409.69 expected, observed/expected ratio (o/e) 1.22, 90% interval 1.13 to 1.31.
Homologues: Orthologues: chimpanzee VASN (99% identical), macaque VASN (96% identical), rabbit VASN (87% identical), dog VASN (87% identical), pig VASN (86% identical), guinea pig VASN (85% identical), rat Vasn (84% identical), mouse Vasn (84% identical), tropical clawed frog vasn (45% identical), zebrafish vasnb (39% identical), zebrafish vasna (39% identical), Caenorhabditis elegans egg-6 (20% identical), and 1 more. Paralogues in human: TLR8 (17% identical), LRRC32 (17% identical), NRROS (16% identical), TLR3 (16% identical), TLR7 (16% identical), TLR5 (16% identical), IGFALS (15% identical), RXFP1 (15% identical), TLR1 (15% identical), TLR6 (15% identical), CD180 (14% identical), TLR2 (14% identical), and 10 more.
Diseases named in the same sentence as VASN in open-access papers:
VASN is named in the same sentence as 54 diseases in open-access papers, as found by Europe PMC text mining. Sharing a sentence is not in itself a finding about the gene and the disease. The quoted sentences say what the papers report.
glioma (8 papers, 2020 to 2025). A benign or malignant brain and spinal cord tumor that arises from glial cells (astrocytes, oligodendrocytes, ependymal cells). "Elevated levels of vasorin have been demonstrated to bind to and prevent the degradation of Notch1 in glioblastoma, and the resulting augmentation of Notch1 stability is thought to account for the vasorin‐associated aggressiveness of glioma." (PMID 35170203, 2022). "For example, the redox-associated genes NCF2, VASN, FKBP1B, and TXNDC2 have been identified as central genes, potentially serving as a dependable prognostic indicator for the clinical management of glioma." (PMID 41049606, 2025). "But the density of hundreds of VASN per square micron is in line with the density of VASN in certain physiological conditions, such as in glioma, as VASN is reported to be overexpressed in certain tumors, including brain tumors." (PMID 38612924, 2024). "Observational studies have found that angiogenic factors (CCR2, VEGF-A, etc.)are overexpressed in glioma cells with high levels of VASN." (PMID 36910644, 2023). "There are many other proteins with pro-angiogenic activity currently under investigation in gliomas, such as the transmembrane protein vasorin, Ras homolog family member 1 (Rho1), and chemokine receptor 2 (CXCR2), along with its ligand CXCL2." (PMID 37626776, 2023). "Overexpression of PCDH18, PPL, DEPP1, VASN, KCNE4, MYBPH, and C5AR2 in glioma and low expression of MARCH4 were associated with poor survival." (PMID 39281062, 2022). "Overexpression of PCDH18, PPL, DEPP1, VASN, KCNE4, MYBPH, and C5AR2 genes or low expression of MARCH4 gene in glioma patients was associated with poor survival." (PMID 39281062, 2022). "Some studies found that glioma patients with high VASN expression had a shorter overall survival time." (PMID 39281062, 2022). "Through TCGA database, we identified that the eight key genes (PCDH18, PPL, DEPP1, VASN, KCNE4, MYBPH, C5AR2, and MARCH4) were associated with the survival of patients with glioma." (PMID 39281062, 2022). "VASN stimulates tumor progression and angiogenesis in glioma and represents a novel therapeutic target for glioma." (PMID 39281062, 2022). "The two potential VASN activation pathways as indicated by its monomeric state in the membrane have their own implications for the ongoing therapeutic strategy of targeting VASN, be it in a therapy for glioma or one for other vascular-related conditions." (PMID 38612924, 2024). "Interestingly, NOTCH signaling is also augmented in hypoxic tumor regions by Vasorin-mediated stabilization of NICD, and hypoxia-induced expression of Vasorin promotes glioma aggressiveness." (PMID 33076453, 2020). "Of the 508 patients with glioma, the expression of PCDH18 (p < 0.001), DEPP1 (p < 0.001), VASN (p < 0.001), KCNE4 (p < 0.01), MYBPH (p < 0.001) and MARCH4 (p < 0.01) genes was significantly different between G2 and G3." (PMID 39281062, 2022).
breast carcinoma (4 papers, 2022 to 2024). "Previous studies have suggested that VASN, a protein associated with vascular function, primarily influences vascular function through the TGFβ signaling pathway, and a recent study on breast cancer yielded a similar conclusion." (PMID 39107788, 2024). "The mechanism involved in this inhibitory action of VASN on TGF-beta was revealed in breast cancer cell lines." (PMID 35454907, 2022). "VASN has been reported to be upregulated in breast cancer and hepatocellular cancer, representing a link in tumor progression." (PMID 35233325, 2022). "BB‐94 has been shown to suppress the production of soluble vasorin through inhibition of ADAM17 in MCF7 breast cancer cells." (PMID 35170203, 2022).
cardiac hypertrophy (4 papers, 2022 to 2025). "Our results reveal a pathological phenomenon in which VASN deficiency may lead to cardiac hypertrophy by downregulating MYL7 production." (PMID 34854218, 2022). "Our results indicated that cardiac hypertrophy may be the cause of death in young VASN‐knockout mice." (PMID 34854218, 2022). "To further study the potential molecular mechanism by which VASN deficiency leads to cardiac hypertrophy, we studied whether changes in MYL7 expression affect myocardial fibre structure." (PMID 34854218, 2022). "The obvious increases in cardiovascular risk, heart weight and myocardial volume and the upregulation of hypertrophy marker gene expression indicated that cardiac hypertrophy may be the cause of death in young VASN−/− mice." (PMID 34854218, 2022). "Our results revealed a pathological phenomenon in which VASN deficiency may lead to cardiac hypertrophy by downregulating MYL7 production." (PMID 34854218, 2022). "Therefore, our results reveal a pathological phenomenon in which VASN deficiency may lead to cardiac hypertrophy by downregulating MYL7 expression." (PMID 34854218, 2022). "Cardiac hypertrophy may be the cause of death in young VASN‐knockout mice." (PMID 34854218, 2022). "Our previous study showed that a VASN-knockout mouse model exhibited pathological cardiac hypertrophy symptoms." (PMID 39898320, 2024). "Mechanistically, we discovered that VASN deficiency downregulated MYL7 expression, which induced myocardial structure abnormalities and disorders, resulting in cardiac hypertrophy." (PMID 34854218, 2022). "Approximately 70% of VASN−/− mice had cardiac hypertrophy; this percentage was higher than that in VASN−/+ and VASN+/+ mice (Figure 3B2)." (PMID 34854218, 2022). "In this study, we used CRISPR/Cas9 technology to produce VASN‐knockout mice and investigated the changes in cardiac function and cardiac hypertrophy index values." (PMID 34854218, 2022). "Taken together, these findings show that VASN deficiency reduces MYL7 expression, which leads to cardiac hypertrophy (mechanism diagram)." (PMID 34854218, 2022). "VASN knockout led to pathological cardiac hypertrophy, which may regulate the p‐MLC2 signalling pathway through exosomal miRNA." (PMID 41235503, 2025). "VASN knockout led to pathological cardiac hypertrophy, which may regulate the p‐MLC2 signal pathway through exosomes miRNA (Mechanism diagram)." (PMID 41235503, 2025). "In summary, this study revealed that VASN plays a novel and vital role in cardiac hypertrophy." (PMID 34854218, 2022). "Based on these studies, a novel pathological phenomenon was hypothesized in which VASN deletion leads to cardiac hypertrophy by affecting MYL7 expression." (PMID 34854218, 2022). "The aim of this research was to ascertain whether VASN induces pathological cardiac hypertrophy by targeting myosin light chain 7 (MYL7)." (PMID 34854218, 2022). "The expression of cardiac hypertrophy marker genes (BNP and MYH7) was significantly upregulated in VASN−/− mice compared with VASN+/+ mice (Figure 3B3‐B4)." (PMID 34854218, 2022). "To date, it has not been reported whether VASN deficiency causes cardiac hypertrophy." (PMID 34854218, 2022). "The absence of VASN also contributed to increased heart weight and cardiomyocyte size, indicating cardiac hypertrophy." (PMID 38975316, 2024). "Vasorin knockout (VASN−/−) leads to pathological cardiac hypertrophy (PCH); however, it is not yet clear whether this PCH transitions to MF in mice." (PMID 39898320, 2024).
liver cancer (4 papers, 2015 to 2025). An epithelial or non-epithelial malignant neoplasm that arises from the liver. "Studies have shown that VASN protein has a cancer-promoting effect and may be closely related to the occurrence and development of liver cancer." (PMID 39281062, 2022). "As a membrane protein and/or free protein,VASN may be an effective target for biological treatment of liver cancer and a potential biomarker for the diagnosis of liver cancer." (PMID 30379973, 2018). "It is interesting that VASN, as a membrane protein, was found to promote cell proliferation and migration, which may also be a potential drug target for treatment of liver cancer." (PMID 25826090, 2015). "Furthermore, among the 37 cases of AFP negative sera (37%), 23 cases (62%) were VASN positive (≥ 1.5061ng/ml), which suggested that combining the use of AFP and VASN could improve the sensitivity of liver cancer diagnosis." (PMID 25826090, 2015). "In addition, blocking membrane VASN with a VASN antibody did not cause significant changes in the cell phenotype, indicating that the effect of VASN on liver cancer cells might be attributed to sVASN." (PMID 40430053, 2025).
atherosclerosis (3 papers, 2024). A disease characterized by the build-up of fatty material and calcium deposition in the arterial wall resulting in partial or complete occlusion of the arterial lumen. "In atherosclerosis, abnormal expression of the VASN gene can cause endothelial dysfunction, reduce the resistance of the vascular endothelium to lipid deposition, and promote the formation of atherosclerotic plaques." (PMID 39898320, 2024). "In addition, previous findings suggest that VASN levels in the blood or vascular tissue are significantly associated with the onset and development of hypertension and atherosclerosis." (PMID 38975316, 2024). "VASN may regulate the expression of adhesion molecules on the surfaces of endothelial cells, increase the adhesion of leukocytes to the vascular walls, and trigger inflammatory reactions to accelerate atherosclerosis." (PMID 39898320, 2024). "Vasorin plays a role in arterial response to injury and PCYOX1 is a pro-oxidant enzyme known to be involved in heightened oxidative stress, tissue inflammation, and thickening/hardening of the arteries of atherosclerosis." (PMID 38673938, 2024).
glioblastoma (3 papers, 2018 to 2024). The most malignant astrocytic tumor (WHO grade IV). "Vasorin has been reported to possess tumour growth promoting activity in glioblastoma cells, anti‐apoptotic activity, and to exhibit upregulated expression in mouse embryonic fibroblasts under hypoxic conditions." (PMID 35170203, 2022). "Similarly, HIF2α contributes to glioblastoma progression by regulating genes such as GPx1, vasorin, beclin-1, and galectin-3, thereby influencing the response to oxidative stress, angiogenesis, autophagy, and cell survival." (PMID 38893207, 2024).
hepatocellular carcinoma (3 papers, 2015 to 2022). A malignant tumor that arises from hepatocytes. "VASN is abundantly secreted in vascular smooth muscle cells of the aorta and upregulated in breast and hepatocellular cancers, representing a link in tumor progression." (PMID 35233325, 2022). "The results confirmed that vasorin was relatively highly expressed in human hepatoma HepG2, SMMC-7721 cells." (PMID 25826090, 2015). "All these results suggested that VASN could be a functional target of miR145 and miR146a, and that low expression of miR145 and miR146a may result in the abnormally high expression of VASN in hepatoma cells." (PMID 25826090, 2015). "Among these miRNAs, real-time PCR indicated that miR146a, miR145, miR205 and miR3619 had relatively lower expression in hepatoma cell lines of HepG2 and SMMC-7721, which have high expression of VASN." (PMID 25826090, 2015). "Vasorin (VASN) is a type I transmembrane protein that plays an important role in tumor development and vasculogenesis; it is a potential serum biomarker of hepatocellular carcinoma and it may be a drug target for its treatment." (PMID 30813269, 2019). "We found that the levels of miR145, miR146a and miR146b were lower in 5 cases of AFP negative hepatoma patients sera compared with those in 4 cases of normal sera, showing a negative correlation with the expression level of VASN." (PMID 25826090, 2015). "Our results showed that the level of VASN was higher in sera of 100 cases of hepatocellular carcinoma compared with 97 normal cases and 129 cases of B type hepatitis, consistent with the higher expression of VASN in HCC cell lines and HCC tissues both at the mRNA and protein levels." (PMID 25826090, 2015). "We report a new biomarker of hepatocarcinoma, vasorin (VASN), screened by a subtractive EMSA-SELEX strategy from AFP negative serum of hepatocellular carcinoma (HCC) patients with extrahepatic metastases." (PMID 25826090, 2015).
IgA nephropathy (3 papers, 2019 to 2024). "Urinary exosomal aminopeptidase N, vasorin precursor, α-1-antitrypsin, and ceruloplasmin could differentiate IgA nephropathy from thin basement membrane nephropathy and healthy controls." (PMID 32082158, 2019). "For other glomerular diseases, a previous study using a proteomics approach has shown that urinary exosomal aminopeptidase N, vasorin precursor, α-1-antitrypsin, and ceruloplasmin could differentiate immunoglobulin A (IgA) nephropathy from thin basement membrane nephropathy and healthy controls." (PMID 32082158, 2019).
thin basement membrane nephropathy (3 papers, 2019 to 2022). "Higher levels of aminopeptidase N, vasorin precursor, α-1-antitrypsin, and ceruloplasmin have been used to distinguish between IgA and thin basement membrane nephropathy which is another common cause of glomerular hematuria." (PMID 32849923, 2020).
aortic valve calcification (2 papers, 2018 to 2024). "Reduction of circulating vasorin is closely correlated with the incidence and severity of aortic valve calcification in humans." (PMID 29930755, 2018). "Notably, tissue VASN protein levels exhibit a negative correlation with the degree of post‐injury arterial restenosis in an experimental animal model, and low circulating VASN levels are closely associated with the prevalence and severity of aortic valve calcification in humans." (PMID 38975316, 2024).
brain tumors (2 papers, 2023 to 2024). "Namely, the correlation between brain tumors and VEGF may be due to the upregulation of the VEGF concentration by VASN." (PMID 36910644, 2023).
colon cancer (2 papers, 2022 to 2024). "The rectal cancer cell line SW837 exhibited higher expression of VASN than did the colon cancer cell lines LOVO and T84 at both the RNA and protein levels." (PMID 39107788, 2024). "The objective of this study was to investigate the utility of vasorin, a newly discovered transmembrane protein, as a novel biomarker in the early detection of colon cancer." (PMID 35233325, 2022). "In this study, we investigated the utility of vasorin as a novel biomarker in the early diagnosis of colon cancer." (PMID 35233325, 2022). "Therefore, the objective of this study was to investigate the utility of vasorin as a novel biomarker in the early detection of colon cancer." (PMID 35233325, 2022). "In addition, we think that studying vasorin levels that are easy to obtain non-invasively will contribute to what is known regarding the early detection of colon cancer." (PMID 35233325, 2022). "Serum Vasorin levels were higher in patients with colon cancer than in the control group (p<0.001)." (PMID 35233325, 2022). "Our findings revealed that serum vasorin levels are upregulated in patients with colon cancer." (PMID 35233325, 2022). "Raised vasorin levels may be a non-invasive biomarker beneficial for early detection and prediction of colon cancer prognosis." (PMID 35233325, 2022).
colorectal cancer (2 papers, 2024 to 2025). A primary or metastatic malignant neoplasm that affects the colon or rectum. "Our pan-cancer analysis indicated that the expression level of VASN (a specific gene of interest) was elevated in patients with pulmonary metastasis, not only in colorectal cancer (CRC) but also in various gastrointestinal tumors." (PMID 39107788, 2024). "Experiments in vitro and in vivo demonstrated that VASN could promote the cell proliferation, metastasis, and drug resistance of colorectal cancer." (PMID 39107788, 2024).
diabetic nephropathy (2 papers, 2018 to 2022). "VASN has also been isolated as a glycoprotein in plasma of patients with diabetic nephropathies." (PMID 30564578, 2018). "Along this line, vasorin has been identified as a potential biomarker of severe progressive nephropathies such as Immunoglobulin A nephropathy (IgAN), thin basement membrane nephropathy (TBMN), or diabetic nephropathy (DN)." (PMID 30564578, 2018).
endothelial dysfunction (2 papers, 2024 to 2025). In vascular diseases, endothelial dysfunction is a systemic pathological state of the endothelium (the inner lining of blood vessels) and can be broadly defined as an imbalance between vasodilating and vasoconstricting substances produced by (or acting on) the endothelium. "Furthermore, we recently reported that a decrease in EVs-VASN in the plasma of severe PE) patients mediates endothelial dysfunction." (PMID 41311505, 2025).
Hypertension (2 papers, 2024). The presence of chronic increased pressure in the systemic arterial system. "Under hypertension, the pressure on the vascular wall increases, and VASN affects the tension and compliance of blood vessels by regulating the contraction and relaxation of the vascular smooth muscle cells." (PMID 39898320, 2024).
Obesity (2 papers, 2016 to 2025). Accumulation of substantial excess body fat. "The genes found to be positively selected in Enshi pigs are involved in crucial biological processes such as body size and immunity (RPS10 and VASN), obesity (GSK3), male fertility (INSL6), and early development (TBX19)." (PMID 27808243, 2016). "Notably, in men with obesity and DM2, the genes up-regulated due to bright light include fibroblast growth factor 1 (FGF1), vasorin (VASN), ribonuclease A family member 1 (RNASE1), pappalysin 1 (PAPPA), Interleukin 7 (IL7), and fatty acid binding protein 3 (FABP3)." (PMID 40981208, 2025).